S100A1 (S100 calcium binding protein A1)
Diseases named in the same sentence as S100A1 in open-access papers (continued):
Sharing a sentence is not in itself a finding about the gene and the disease.
osteoarthritis (2 papers, 2007 to 2023). A noninflammatory degenerative joint disease occurring chiefly in older persons, characterized by degeneration of the articular cartilage, hypertrophy of bone at the margins and changes in the synovial membrane. "S100A1 has previously been reported to be downregulated in osteoarthritis." (PMID 17935617, 2007).
osteosarcoma (2 papers, 2023 to 2024). A usually aggressive malignant bone-forming mesenchymal neoplasm, predominantly affecting adolescents and young adults. "Specifically, the EMT score of S100A1+ cells were significantly higher than that of TMSB4X+ and SLPI+ cells, suggesting that osteosarcoma cells in the TMSB4X+ cells exhibit a greater migration ability, possibly associated with an increased propensity for metastasis." (PMID 39742274, 2024).
pulmonary diseases (2 papers, 2021 to 2022). "Although predominantly expressed in cardiomyocytes, S100A1 is also present in lung endothelium and its increased serum level has been documented in several pulmonary diseases." (PMID 35409008, 2022).
uveal melanoma (2 papers, 2020 to 2022). A melanoma derived from melanocytes of the uveal tract. "It was found that S100A1 was more frequently expressed in conjunctival and uveal melanoma than in conjunctival naevi." (PMID 35269741, 2022). "A previous study compared S100A1 in paraffin-embedded sections of conjunctival naevi, conjunctival melanomas, and uveal melanomas." (PMID 35269741, 2022).
Ventricular arrhythmia (2 papers, 2024 to 2025). "S-nitrosylation of caveolin-1 heightens the risk of ventricular arrhythmia, whereas S-nitrosylation of RyR2, SERCA2, S100-A1, and L-type Ca2+ channels supports cardiac rhythm stability." (PMID 40867518, 2025).
adenoma (1 paper, 2020). A neoplasm arising from the epithelium. "S100A1 protein expressions are marginally higher in the colon connective tissues of normal samples and adenoma with low-grade dysplasia than CRC tissues and high-grade dysplastic lesions." (PMID 33294444, 2020).
Aortic dissection (1 paper, 2023). Aortic dissection refers to a tear in the intimal layer of the aorta causing a separation between the intima and the medial layers of the aorta. "The plasma concentration of S100A1 in patients with acute aortic dissection is significantly increased, pointing to potential clinical value in diagnosing acute aortic dissection." (PMID 37217870, 2023).
atopic dermatitis (1 paper, 2025). "Additionally, S100A1 was found to be hypermethylated in our sample, and similar studies have also identified hypermethylated regions in this gene in adolescents with multi-food allergies and in children with atopic dermatitis." (PMID 41394805, 2025).
brain injury (1 paper, 2025). Acute and chronic (see also brain INJURIES, CHRONIC) injuries to the brain, including the cerebral hemispheres, CEREBELLUM, and brain STEM. "In response to acute CNS injuries, including traumatic brain injury (TBI) or ischemic stroke, the expression of S100 proteins (most notably S100B, S100A1, and S100A8/A9) is markedly upregulated, reaching maximal levels within hours to several days after the insult." (PMID 40867570, 2025).
cancers of kidneys (1 paper, 2015). "However, S100A1 is up-regulated only in cancers of kidneys, skin and ovary." (PMID 26682543, 2015).
cardiac hypertrophy (1 paper, 2019). "It is also proposed that S100A1 could maintain normal adult gene expression in myocardial tissue to inhibit cardiac hypertrophy." (PMID 31523180, 2019).
cerebral infarction (1 paper, 2023). An ischemic condition of the brain, producing a persistent focal neurological deficit in the area of distribution of the cerebral arteries. "The correlation between S100A1, NF-κB p65, and IL-6 levels and cerebral infarction volume was detected by Pearson correlation analysis." (PMID 36643631, 2023). "This study also investigated the relationship between plasma S100A1 and cerebral infarct size, and there was a statistically significant difference between the two (r = 0.259, P < 0.05), but the correlation coefficient was low." (PMID 36643631, 2023). "In summary, our study indicated that the plasma S100A1 protein was significantly correlated with the diagnostic value of AIS and the volume of cerebral infarction." (PMID 36643631, 2023). "Plasma S100A1, NF-κB P65, and IL-6 significantly differed from cerebral infarction volume." (PMID 36643631, 2023). "In exploring the differences in plasma S100A1 levels in acute ischemic strokes of different severity, it was found that there was variability in S100A1 levels in patients with different volumes of cerebral infarction." (PMID 36643631, 2023). "At the same time, the correlation between plasma S100A1 protein and cerebral infarct volume was proposed in this study, and the results showed that its level could reflect the severity of AIS to some extent." (PMID 36643631, 2023). "It was rational to speculate that the S100A1 protein might play a role in a similar pathophysiological process in cerebral infarction." (PMID 36643631, 2023). "There was no significant positive correlation between plasma S100A1 and cerebral infarction volume (R < 0.3), but there was statistical significance (r = 0.259, P = 0.002)." (PMID 36643631, 2023).
cholesteatoma (1 paper, 2014). A pathologic process characterized by the proliferation of keratinizing squamous epithelium resulting in the accumulation of keratin and cells in the middle ear and/or mastoid. "A study that compared the expression of S100A1, 2, 3, 4, 5, 6, and S100B in different epithelial lesions in the head and neck found these proteins to be most frequently expressed in craniopharyngeomas and cholesteatomas." (PMID 25093596, 2014).
developmental delay (1 paper, 2013). "While S100-A1 immunofluorescence intensity appeared to be lower in hypothyroid than in control conditions at P0, by P3, S100-A1 immunofluorescence appeared higher in hypothyroid than in control conditions, which is consistent with the developmental delay observed in hypothyroid cochleae." (PMID 23394545, 2013).
dilated cardiomyopathies (1 paper, 2017). "Uncontrolled S100A1 expression has been linked to HF in human dilated cardiomyopathies as well as in various HF animal models." (PMID 28427148, 2017).
endometrioid ovarian cancer (1 paper, 2018). "In addition, although we found no significant OS prognostic value of S100A1 expression, it signifies poor PFS (progressive free survival) for endometrioid ovarian cancer patients." (PMID 30558666, 2018).
glaucoma (1 paper, 2021). Increased pressure in the eyeball due to obstruction of the outflow of aqueous humor. "Since S100A1 can be secreted in the extracellular space, where high amplitude Zn2+ fluctuations are observed, we propose that it can contribute to pathogenesis of Zn2+-dependent neurodegenerative diseases such as AD and glaucoma." (PMID 34944467, 2021). "In addition, S100A1, together with amyloid peptides, was detected in the aqueous humor of glaucoma patients." (PMID 34944467, 2021). "Moreover, we demonstrate that an excess of Zn2+ produces a destabilizing effect on S100A1 structure and leads to the aggregation of the protein, which could contribute to its neurotoxicity under the pathological conditions of glaucoma and AD." (PMID 34944467, 2021).
leiomyoma (1 paper, 2023). A well-circumscribed benign smooth muscle neoplasm characterized by the presence of spindle cells with cigar-shaped nuclei, interlacing fascicles, and a whorled pattern. "Our data, demonstrating decreased expression of S100A4 and S100A1 particularly in mutated tumors and the increase in CACNA1D expression, suggest potential reduced binding of calcium and greater calcium entry into leiomyoma cells which could contribute to tumor calcification." (PMID 36835153, 2023).
limb ischemia (1 paper, 2013). A ischemia that involves the limb. "We had demonstrated greatly reduced S100A1 levels in mal-perfused muscle tissue of both human patients with CLI and mice after induction of limb ischemia by FAR." (PMID 24244340, 2013). "Pathophysiologic relevance may be derived from the observation that S100A1 levels are severely downregulated, while MiR-138 levels are increased, in both human muscle biopsies procured from patients with CLI, as well as mice with induced limb ischemia." (PMID 24244340, 2013).
medulloblastoma (1 paper, 2020). A malignant, invasive embryonal neoplasm arising from the cerebellum. "The expressions of S100A1, S100A4, S100A10, and S100A11 are regulated by DNA methylation in medulloblastoma and may have potential impacts on the disorder of telencephalon in cerebral hernia." (PMID 32867218, 2020).
ovarian serous carcinoma (1 paper, 2012). "Using TMAs representing 215 ovarian serous carcinoma specimens stained for S100A1, we assessed the degree to which data obtained using computer-aided methods correlated with data obtained by pathologist visual scoring." (PMID 22515559, 2012).
retinitis pigmentosa (1 paper, 2024). Retinitis pigmentosa (RP) is an inherited retinal dystrophy leading to progressive loss of the photoreceptors and retinal pigment epithelium and resulting in blindness usually after several decades. "The expression of Müller cell gliosis genes known to be dysregulated in retinal pathologies such as retinitis pigmentosa, but also in DR, such as Stat3, S100a1 or CD44, were plotted to further validate the gliotic activation in our db/db mice at the molecular level." (PMID 38273366, 2024).
rotator cuff tears (1 paper, 2023). "In summary, this study offers new understanding into the possible use of FDA-approved drugs as treatment options for rotator cuff tears by focusing on the key proteins S100A1 and RASSF8." (PMID 37601265, 2023). "In conclusion, we have identified S100A1 and RASSF8 as potential therapeutic targets for rotator cuff tears." (PMID 37601265, 2023). "In addition, through animal experiments, it was found that Butanediamide can significantly inhibit the expression of S100A1 and RASSF8, and promote healing of rotator cuff tears." (PMID 37601265, 2023). "In summary, both S100A1 and RASSF8 may promote the healing of rotator cuff tears by enhancing angiogenesis and inhibiting cell apoptosis." (PMID 37601265, 2023).
serous ovarian cancer (1 paper, 2018). "Notes: (A-C) Survival curves of S100A1 (the desired Affymetrix IDs is valid: 205334_at) are plotted for all/endometrioid/serous ovarian cancer patients." (PMID 30558666, 2018).
thyroid cancer (1 paper, 2021). "In this study, S100A1 expression in human PTC was investigated to determine its diagnostic utility in thyroid cancers." (PMID 34475990, 2021). "Kaplan-Meier survival curve analysis showed that thyroid cancer patients expressing higher S100A1 had a less favorable RFS." (PMID 34475990, 2021). "Methylation level of S100A1 gene promoter in thyroid cancer was lower than in normal thyroid tissue, which suggested difference in gene expression might due to different methylation levels." (PMID 34475990, 2021). "However, the biological functions of S100A1 in thyroid carcinoma have not been thoroughly studied." (PMID 34475990, 2021).
type I diabetes (1 paper, 2021). "S100A1 expression is dysregulated in type I diabetes, which is characterized by altered Zn2+ homeostasis." (PMID 34944467, 2021).
tumor (52 papers, 2011 to 2026). "It was found that large tumor size and low tumor differentiation were associated with S100A1 expression." (PMID 37133437, 2023). "S100A1 protein expression was significantly associated with tumor size (p=0.0032) or lymph node metastasis (p=0.0331)." (PMID 34475990, 2021). "Thus, tumor-intrinsic S100a1 loss reshapes the TME from an immune-suppressive to an immune-active state." (PMID 40090947, 2025). "In EC, multiple S100 proteins, including S100A1, S100A2, S100A4, S100A8, and S100A9, have been implicated in tumor proliferation, invasion, epithelial–mesenchymal transition (EMT), and response to chemotherapy." (PMID 41303754, 2025). "In summary, we have reported the ability of tumor-intrinsic S100A1 blockade to remodel the immunologically “cold” TME into an inflamed and immunoactive phenotype, eliciting antitumor immunity and potentiating cancer immunotherapy." (PMID 40090947, 2025). "Knockdown of S100A1 inhibited LLC tumor development, with the lung weight decreasing by approximately 75% and mouse survival prolonged." (PMID 40090947, 2025). "We further examined the effects of tumor-intrinsic S100A1 on tumor-specific CD8+ T-cell responses in vivo." (PMID 40090947, 2025). "Inhibiting tumor-intrinsic S100A1 enabled macrophages and T cells to acquire antitumor properties by activating GM-CSF signaling." (PMID 40090947, 2025). "Box plots show increased expression levels of genes such as S100A1, C2, and SPP1, which are associated with tumor progression and metastasis." (PMID 41288989, 2025). "We also analyzed the ligand-receptor interactions between the different cells, and found that the S100A1+ tumor cells interacted with other cell types through the MDK-NCL receptor-ligand pair." (PMID 39742274, 2024). "The results showed that the expression level of S100A1 is elevated with the increased tumor sizes according to both ELISA and microfluidic chip measurement." (PMID 38417122, 2024). "Cell communication analysis revealed an intricate network between S100A1+ tumor cells and other TME cells." (PMID 39742274, 2024). "These pro-migratory but antiproliferative activities of S100A1 are consistent findings that migratory cells have a lower proliferation rate than those in the less mobile but highly proliferative tumor core." (PMID 35177036, 2022). "S100A1 was reported to control the migration and proliferation of cancer cells and its elevated expression is a known marker of tumor malignancy." (PMID 34944467, 2021). "To confirm our findings with in vivo experiments, we analyzed the impact of S100A1 silencing in xenograft tumor nude mouse models." (PMID 34475990, 2021). "In particular, it is reported that S100A1 and S100A7 are linked to tumor growth, while S100A4 and S100A8 are linked to metastasis." (PMID 28615627, 2017). "S100a1KD promoted the activation and proliferation of CD8+ T cells compared to the scramble control, which was similar to the flow cytometry results and suggested that tumor-intrinsic S100A1 may be involved in modulating T cell-mediated antitumor immunity." (PMID 40090947, 2025). "In HER2-positive disease, our findings associate genes such as ARG2, S100A1, MT2A, EIF4EBP1, KLF4, BTG3, and BAG1 to be associated with favourable prognosis through their roles in metabolic regulation, oxidative stress mitigation, and tumour suppression." (PMID 41007296, 2025). "Tumor cell-intrinsic S100a1 ablation promoted CD8+ T-cell activation and proliferation." (PMID 40090947, 2025). "Moreover, combining S100A1 depletion with anti-PD-1 therapy effectively attenuated LLC tumor growth and increased CD8+ T-cell infiltration." (PMID 40090947, 2025). "Considering S100A1’s involvement in immune suppression and tumor progression, we explored whether S100A1 depletion influences the tumor immune microenvironment (TIME) via flow cytometry." (PMID 40090947, 2025). "We observed that tumor cell-intrinsic S100A1 mRNA expression was induced upon ICB." (PMID 40090947, 2025).
tumor (continued). "The S100A1+ tumor cells in particular showed strong interaction with other TME cells." (PMID 39742274, 2024). "Furthermore, in vivo microneedle‐assisted sampling of S100A1 was conducted using the mice animal model with different tumor sizes." (PMID 38417122, 2024). "S100A1 knockdown inhibited tumor progression as seen in in vivo experiments." (PMID 34475990, 2021). "High expression of the S100A1 was associated with tumor size (p=0.0032), lymph node metastasis (p=0.0331), but not with gender, age, extrathyroidal extension or bilateral PTC." (PMID 34475990, 2021). "Moreover, reducing S100A1 expression also did not affect tumor progression in immune-deficient BALB/c-nude mice." (PMID 40090947, 2025). "Notably, S100a1 loss delayed LLC tumor growth and prolonged survival in immune-competent C57BL/6J mice, suggesting that T-cell-mediated immunity contributed to the antitumor activity of tumor-intrinsic S100a1 loss." (PMID 40090947, 2025). "Mechanistic investigations demonstrated that interfering with the tumor-intrinsic S100A1/ubiquitin-specific protease 7/p65/granulocyte-macrophage colony-stimulating factor (GM-CSF) modulatory axis could potentiate an inflamed TME by promoting M1-like macrophage polarization and T cell function." (PMID 40090947, 2025). "Thus, s100a1 was required for the krasG12V-induced tumor growth, and the enhanced s100a1 expression in the PH livers may contribute to HCC development in kras+ zebrafish." (PMID 38791872, 2024). "Moreover, the S100A1+ tumor cells exhibited active communication with other cells." (PMID 39742274, 2024). "Notably, genes S100A1 and S100A8, which encode for the calprotectin complex, demonstrated a significant upregulation, with a threefold increase in expression observed in 80% of the tumor samples." (PMID 38979413, 2024). "S100A1, S100A4 and S100B protein expression are related to the increasing levels of tumor malignancy." (PMID 31968004, 2020). "It is of considerable importance that gene expression of S100a4 and S100a11 was up to 34-fold induced in tumours of EGF transgenic mice, however expression of S100a1 was repressed." (PMID 25872475, 2015). "Moreover, it is essential to note that while S100A1 regulates calcium homeostasis in cardiomyocytes, this study did not investigate its role in the calcium regulation in tumor cells." (PMID 40090947, 2025).